ACE (angiotensin I converting enzyme)
Diseases named in the same sentence as ACE in open-access papers (continued):
Sharing a sentence is not in itself a finding about the gene and the disease.
angioedema (continued). "Infection with severe acute respiratory syndrome coronavirus 2 (SARS-CoV-2) is hypothesized to contribute to the development of angioedema by modifying ACE II levels and further increasing the level of bradykinin in patients taking ACE inhibitors." (PMID 38910667, 2024). "Therefore, despite the lack of proven efficacy, exploring potential treatments is valuable in the management of ACE inhibitor angioedema." (PMID 38543146, 2024). "ACE inhibitor-induced angioedema commonly presents with facial and oropharyngeal swelling." (PMID 38546304, 2024). "Individuals with underlying angioedema attributed to C1 inhibitor deficiency or dysfunction, whether hereditary or acquired, can develop bradykinin-mediated angioedema independently of ACE inhibitors." (PMID 38543146, 2024). "Surprisingly, the C1INH treatment was found to be inferior in the treatment of ACE inhibitor-induced angioedema compared to the placebo, specifically concerning the time to complete the resolution of symptoms (29.63 h ± 15.56 h in the C1INH arm and 17.29 h ± 10.40 h in the placebo arm)." (PMID 38543146, 2024). "ACE inhibitors are the leading course of drug-induced angioedema in the USA." (PMID 38543146, 2024). "Additionally, a randomized study involving heart transplant recipients demonstrated that those receiving ACE inhibitors and mTOR inhibitors had a 50–100 times higher incidence of angioedema compared to those on conventional immunosuppression therapy." (PMID 38205154, 2024). "The understanding of ACE inhibitor-induced angioedema has evolved progressively, transitioning from initial data obtained from registration trials and pharmacovigilance databases to more robust insights provided by contemporary large-scale prospective investigations." (PMID 38205154, 2024). "ACE inhibitors are known to accumulate bradykinin levels leading to angioedema development; however, considering anaphylaxis, it is thought that ACE inhibitors, as well as beta-blockers, may act through activation of the high-affinity IgE receptor FcεRI." (PMID 38256923, 2024). "However, these medications, are not without their complexities, and a lesser-known but potentially serious side effect has been emerging—angioedema induced by five-membered nitrogen heterocycles ACE inhibitors." (PMID 38543146, 2024). "In fact, one study of Icatibant therapy for ACE inhibitor angioedema did report excellent results." (PMID 38332896, 2024). "The blood and tissue levels of these enzymes may be particularly important in the prevention of angioedema when ACE has been inactivated." (PMID 38332896, 2024). "Further studies will be needed to demonstrate whether C1 inhibitor can be used effectively in ACE inhibitor-induced angioedema." (PMID 38543146, 2024). "For example, angioedema can occur from ACE inhibitor therapy." (PMID 38435190, 2024). "An additional pharmacovigilance study was conducted examining FDA Adverse Events Report data from 2013 to 2017 and noted that linagliptin had an association with angioedema irrespective of ACE inhibitor use." (PMID 38957198, 2023). "Inhibition of ACE results in decreased degradation of bradykinin, a potent vasodilator and permeability factor, leading to increased levels of bradykinin and subsequent angioedema." (PMID 38957198, 2023). "The diagnosis of ACE inhibitor-associated angioedema is made clinically based on the presence of angioedema without urticaria and pruritus." (PMID 38957198, 2023). "Theoretically, these agents may be effective with other types of bradykinin-induced angioedema, such as ACE inhibitor-induced and acquired angioedema." (PMID 37927771, 2023). "This study investigated the association between DPP-4 inhibitors (DPP-4Is) and angioedema, including cases where the concomitant use of ACE inhibitors (ACEIs) was absent." (PMID 35907939, 2022). "Any patient with recurrent angioedema without wheals nonresponsive to standard CU treatment, not taking ACE inhibitors, should be screened for complement deficiency." (PMID 36238930, 2022).
angioedema (continued). "In contrast with previous evidence, our meta-analysis does not suggest a significant increased risk of angioedema when individuals are exposed to ACE inhibitors (RR = 1.32, 95% CI = 0.90–1.95, p = 0.160)." (PMID 35886227, 2022). "Moreover, omapatrilat, the first dual inhibitor of both neprilysin and ACE, produced a higher incidence of potentially life-threatening angioedema than enalapril, despite its greater efficacy in reducing blood pressure." (PMID 36003518, 2022). "A 2006 systematic review compared the risk of ACE-inhibitor angioedema between 55252 Black and 133964 non-Black patients." (PMID 34508156, 2022). "ACE inhibitor-induced angioedema occurs in 0.1%–2.2% of adults treated with ACE inhibitors." (PMID 34284535, 2021). "– Isolated occurrence of angioedema may indicate bradykinin-mediated angioedema, e.g. HAE or ACE inhibitor/sartan-mediated angioedema." (PMID 33643777, 2021). "Again, the frequency of ACE inhibitor-induced angioedema was found to be higher in women." (PMID 34284535, 2021). "The most important cause of angioedema without urticaria was drugs (79.4%), and angiotensin converting enzyme (ACE) inhibitors were responsible for 60.4% of them and NSAIDs for 13.9%." (PMID 34284535, 2021). "Among the most recognized examples of adverse side effects afforded by ACE inhibitors are cough (experienced by 5–20% of patients) and angioedema (experienced by 0.1–0.5% of patients), both of which are associated with elevated levels of bradykinin and substance P in patients taking these drugs." (PMID 33687143, 2021). "Thus, DPP-4 inhibitor-induced angioedema should be carefully considered and monitored, especially during concurrent treatment with ACE inhibitors." (PMID 34884209, 2021). "Vasoactive peptide-induced angioedema may onset not only in ACE inhibitors but also in DPP-4 inhibitors." (PMID 34884209, 2021). "Angioedema is one of the dreaded side effects of angiotensin-converting enzyme (ACE) inhibitors." (PMID 34917435, 2021). "Furthermore, signals of angioedema with the combination of ACE and DPP-4 inhibitors have been reported in research using the WHO pharmacovigilance database." (PMID 34884209, 2021). "Icatibant is effective for ACE inhibitor-triggered angioedema, which is also involved in the enhancement of bradykinin production, suggesting that treatment based on etiology is essential for the treatment of angioedema." (PMID 34445711, 2021). "ACE inhibitor-induced angioedema may remit spontaneously, but many angioedemas relapse with the continued use of ACE inhibitors." (PMID 34884209, 2021). "A mixed ACE-neprilysin inhibitor, omapatrilat, has been designed and tested in clinical trials but eventually not approved for clinical use because of its poor tolerance with a high incidence of angioedema." (PMID 33800422, 2021). "This dose has been used successfully for the management of ACE inhibitor-induced angioedema and hereditary angioedema {Baş, 2015, A randomized trial of icatibant in ACE-inhibitor-induced angioedema}{Cicardi, 2010, Icatibant’, a new bradykinin-receptor antagonist’, in hereditary angioedema}." (PMID 33472675, 2021). "Of importance, ACE inhibitor-related angioedema occurs several months after its last dose." (PMID 33398469, 2021). "ACE‐inhibitor associated angioedema was universally categorized as allergy although it is nonimmunological, although angioedema does not appear in the drop‐down list of reactions for intolerances." (PMID 32302059, 2020). "Furthermore, these lists are technically incorrect, such that, for example, angioedema is available only in the allergies list, but it is an adverse effect of the pharmacological action of ACE‐inhibitors, and is therefore, an intolerance." (PMID 32302059, 2020). "Another issue regarding ACEi-AE is that some cases might suffer from rare types of angioedema i.e. hereditary angioedema associated with factor XII mutations, which could be ‘set off’ by the ACE inhibition." (PMID 31710633, 2019).
angioedema (continued). "It preserves the ACE mechanism for bradykinin degradation and protects from angioedema formation." (PMID 31336656, 2019). "A well-known adverse drug reaction to ACE inhibitors is ACE inhibitor-induced angioedema (ACEi-AE)." (PMID 31710633, 2019). "Therefore, ACE inhibitors should be discontinued in all individuals with angioedema, and are absolutely contraindicated in patients with either HAE or AAE." (PMID 30263036, 2018). "ACE inhibitor-induced angioedema can be life-threatening when it involves the upper airway." (PMID 30263036, 2018). "Considering that ACE inhibitor induced angioedema pathophysiologic mechanisms are similar to the hereditary angioedema, several novel therapies available for treatment of hereditary angioedema may be effective in ACE inhibitor induced angioedema management." (PMID 30075570, 2018). "It is important to note that cortisone and antihistamines are clearly ineffective in some types of angioedemas (HAE-C1-INH, HAE with normal C1-INH, angioedemas caused by acquired C1-INH deficiency, angioedemas caused by ACE inhibitors) and only questionably effective in others." (PMID 31826031, 2018). "Episodes of angioedema may occur up to 1 month (or sometimes more) after discontinuing the ACE inhibitor." (PMID 30263036, 2018). "KLK-1 release from vascular or other cell types could be a trigger for ACE inhibitor-induced angioedema, a condition reportedly resistant to ecallantide and probably to the B2R antagonist icatibant." (PMID 30333824, 2018). "Additionally, it includes ACE inhibitor use and area of infarct to allow for comparisons to already established notions of tPA-induced angioedema." (PMID 30363665, 2018). "However, there is low awareness of enalapril/ACE inhibitor-induced angioedema among medical personnel." (PMID 29974027, 2018). "Thus, the plasma half-life of bradykinin is extended in patients taking ACE inhibitors, thereby increasing the plasmatic concentration in case of bradykinin generation, that can more easily reach a level triggering angioedema." (PMID 30018956, 2018). "Notably, concurrent use of ACE inhibitors is also reported in patients who developed angioedema during r-tPA treatment." (PMID 27122021, 2016). "However, given the recognized role of kinin peptides in ACE inhibitor-induced angioedema the additional downgrading of kinin metabolism by NEP inhibition would be predicted to increase the occurrence of angioedema." (PMID 26637405, 2016). "Additionally, the B2R antagonist, icatibant (Shire), has been the subject of clinical trials both for HAE, and for ACE inhibitor-induced angioedema, and received FDA approval to treat acute HAE in 2011." (PMID 27618014, 2016). "Thus, the patient was treated with plasma-derived C1-esterase inhibitor (Berinert) since there have been previous reports regarding the efficacy of this drug in severe ACE-inhibitor related angioedema." (PMID 27123347, 2016). "The cause of angioedema was identified in 59/161 (37%) of the cases: 3 (2%) patients had a low plasma C1-INH and C4; 20 (12%) were ACE inhibitor-induced; 12 (7%) were associated with autoimmune disorders; 7 (4%) were associated with malignancy; and 17 (11%) were associated with NSAIDs." (PMID 25670937, 2014). "Furthermore, cough and angioedema are more frequent in women than in men during treatment with ACE-inhibitors." (PMID 25364906, 2014). "This patient had several risk factors for severe angioedema: the therapy with ACE inhibitor which was not stopped, older age, Hispanic race, class III of Anesthesiologist's American Society, and coexistent cardiopulmonary disease." (PMID 25431681, 2014). "Many medications can cause angioedema but those most commonly implicated are angiotensin-converting enzyme (ACE) inhibitors and nonsteroidal anti-inflammatory drugs (NSAIDs)." (PMID 24792779, 2014). "Perioperative ACE inhibitor angioedema is a rare occurrence but can be life-threatening." (PMID 25431681, 2014).
angioedema (continued). "Gastrointestinal involvement can be seen in HAE, AAE, and ACE inhibitor-induced angioedema." (PMID 24792779, 2014). "After the ACE inhibitors withdraw, the probability of angioedema lowers with the passing time." (PMID 25431681, 2014). "These patients develop sporadic angioedema of the face while on ACE inhibitors." (PMID 22340023, 2012). "The AACVS pattern of symptoms would be very consistent with low levels of ACE activity, producing both inadequate or delayed A2 generation to prevent hypotension and impaired BK metabolism that could facilitate angioedema." (PMID 23316249, 2012). "Isolated angioedema also occurs in approximately 0.1% to 6% of individuals using ACE inhibitors." (PMID 22165855, 2011). "Like HAE and AAE, ACE inhibitor–induced angioedema is bradykinin-mediated." (PMID 22165855, 2011). "Angioedema can occur in the absence of urticaria, with angiotensin-converting enzyme (ACE) inhibitor-induced angioedema and idiopathic angioedema being the more common causes." (PMID 22165855, 2011). "• Angioedema can occur in the absence of urticaria, with ACE inhibitor-induced and idiopathic angioedema being the most common causes." (PMID 22165855, 2011). "Most cases of angioedema occur in the first week after starting ACE-inhibitor therapy." (PMID 22165855, 2011). "Many cases of angioedema are nonallergic reactions, for example, bradykinin-induced angioedema caused by genetic defects and angiotensin-converting enzyme (ACE) inhibitors." (PMID 20161864, 2009). "The second pathway is the kinin pathway, most notably affected by angiotensin converting enzyme (ACE) inhibitors and hereditary forms of angioedema with C1-esterase inhibitor defects, which ultimately results in the formation of bradykinin, a potent vasodilator." (PMID 20066173, 2009). "However, while most cases of ACE-inhibitor-induced angioedema resolve upon discontinuation of the offending drug and use of corticosteroids, the use of epinephrine in our case was particularly significant given the rapid onset of tongue swelling and the potential for airway obstruction." (PMID 40636633, 2025). "It stresses the urgent need for clinicians to differentiate this condition from other forms of angioedema, particularly mast cell-mediated types, as early recognition and long-term monitoring are crucial given the possibility of recurrence even after discontinuation of ACE inhibitors." (PMID 38543146, 2024). "Importantly, angioedema may reappear, even after cessation of ACE inhibitors, and persist for months." (PMID 38543146, 2024). "However, while generally assumed to be true, bradykinin has not been proven to cause angioedema due to angiotensin converting enzyme inhibitors (ACE-inhibitors), and drug trials using agents to block bradykinin have not given clear results." (PMID 38332896, 2024). "Notably, patients solely on ACE inhibitor therapy exhibited angioedema in 2.2% of cases." (PMID 38205154, 2024). "Angioedema caused by ACE inhibitors is usually never associated with urticaria." (PMID 38435190, 2024). "Nineteen cases of angioedema have been reported by vildagliptin among which 73% were using ACE inhibitors concurrently, in one meta-analysis no significant increase in angioedema risk was seen with vildagliptin (without ACE inhibitors) compared to placebo or other oral hypoglycemic agents." (PMID 38523307, 2024). "Our literature search identified one study among Africans which reported on the angiotensin-converting enzyme gene insertion/deletion (I/D) polymorphism, while establishing an association of the 9/+9 insertion/deletion polymorphism in the B2 gene with ACE-induced angioedema and cough." (PMID 38633331, 2023). "Furthermore, it is possible that the trials did not have a follow-up period long enough to detect the incidence of angioedema, because more than half of the cases showing this adverse consequence may occur after one year (or longer) of ACE inhibitor treatment." (PMID 35886227, 2022).
angioedema (continued). "However, the occurrence of angioedema is known to be related to the inhibition of bradykinin degradation, and sacubitril/valsartan does not inhibit ACE or aminopeptidase P, so it does not increase the risk of angioedema." (PMID 36158828, 2022). "– Taking ACE inhibitor or sartan may indicate ACE inhibitor/sartan-mediated angioedema." (PMID 33643777, 2021). "Therefore, vasoactive peptide-induced angioedema may onset not only in ACE inhibitors but also in DPP-4 inhibitors." (PMID 34884209, 2021). "Angiotensin-converting enzyme (ACE) inhibitors are recommended for use in all individuals with left ventricular systolic dysfunction or HfrEF, irrespective of functional class, except in those cases of intolerance or a contraindication, such as angioedema exists." (PMID 33542867, 2021). "However, there are some subtypes of angioedema that do not respond to anti-histamine, such as angioedema due to C1-inhibitor deficiency, angioedema due to ACE inhibitors and a rate of idiopathic angioedema." (PMID 31281319, 2019). "Therefore, consideration should be given to whether a PLG defect should be investigated in all cases of ACE inhibitor-induced angioedema." (PMID 30809376, 2019). "Mechanism and level of risk are not always obvious (for example, angioedema with an ACE-inhibitor is intolerance not allergy; the reaction may be moderate, but contraindication is absolute) and need not be specified at the time of ADR entry." (PMID 30923609, 2019). "The increased risk of angioedema with combination DPP-4 and ACE inhibitor therapy is one potential limitation, however, this issue may be managed by consideration of replacing an ACE inhibitor with an ARB." (PMID 29669555, 2018). "However, bradykinin is also an important contributor to angioedema that may result from peptidase inhibitor therapy, including neprilysin inhibitor therapy, particularly when neprilysin inhibition is combined with ACE inhibitor therapy." (PMID 30283782, 2018). "Moreover, the time of presentation of the angioedema in relation to ACE inhibitor therapy varies." (PMID 30075570, 2018). "However, ACE inhibitors induced angioedema after cervical surgery is a rare condition." (PMID 28348897, 2017). "Thus, it may be that when neprilysin and ACE are inhibited at the same time, bradykinins accumulate, which in turn results in cough and angioedema." (PMID 29296218, 2017). "ACE inhibitors are the most common cause of nonhereditary angioedema (25–39%)." (PMID 25431681, 2014). "Our results suggest that anaphylactic reactions to foods, venom, and drugs which involve acute angioedema and cardiovascular collapse may have links with II and ID ACE genotypes and lower serum ACE levels, which is less clearly related to the conventional anaphylaxis Grades I–IV." (PMID 23316249, 2012). "Angioedema in the absence of urticaria is rare and should alert the physician to alternative diagnoses, such as hereditary or acquired angioedema, idiopathic angioedema, or angioedema associated with angiotensin-converting enzyme (ACE) inhibitors." (PMID 22165855, 2011). "The ACE inhibitors can induce urticariform reactions, bullous lesions and phototoxic reactions, in particular captopril which contains a thiol group as with angioedema, usually without associated urticaria." (PMID 20180980, 2010). "However, laryngeal edema and edema of the bowel is not seen, thus it differs from the angioedema associated with ACE inhibitors or C1 INH deficiency." (PMID 23282406, 2008). "C1 INH deficiency (hereditary and acquired) presents with angioedema and does not have associated urticaria, ACE inhibitor angioedema, may have minor urticaria, but angioedema is clearly the main problem, and idiopathic angioedema has no hives, by definition." (PMID 23282406, 2008). "There is a need to further understand the interplay between ACE inhibitors and SARS-CoV-2 in the development of angioedema, especially in the African American population." (PMID 38910667, 2024).